TGFA (transforming growth factor alpha)
Diseases named in the same sentence as TGFA in open-access papers (continued):
Sharing a sentence is not in itself a finding about the gene and the disease.
tumor (continued). "HGSOC production of TGFα drives monocytes to differentiate into macrophages, representing a central arm of the mechanism by which AAMs are generated in the tumor microenvironment." (PMID 33069212, 2020). "The complexity of the mechanisms involved is further amplified by the ability of TGFα to act in a paracrine manner to modulate the tumor microenvironment." (PMID 32517259, 2020). "These tumor cells further exhibit overexpressed growth factors and receptors, such as the transforming growth factor alpha (TGFA) and the epidermal growth factor receptor (EGFR) based on mutations." (PMID 31952211, 2020). "The prolonged survival correlated with reduced secretion of TGF-β1 and TGFα as well as decreased phosphorylation of SMAD2 in the brain suggesting reduced cytokine secretion by the tumour cells upon reduced SPP expression." (PMID 32052089, 2020). "In 1993, Rusch and colleagues demonstrated that the protein expression of EGFR is significantly increased in 45% of tumour lesions from NSCLC patients, while TGFα was overexpressed in 61% of those tumours." (PMID 31438559, 2019). "To test the concept that these liver localized IL-12/15/18 primed NK cells would have anti-tumor activity we injected c-Myc/TGFα double Tg mice via the tail vein with PBS or with purified NK cells." (PMID 30467624, 2019). "Of the EGFR ligands, amphiregulin, BTC, EGF, and TGFα were expressed in the cytoplasm of 50%, 76%, 70%, and 73% of the tumours respectively." (PMID 30899442, 2019). "Increased proliferation and angiogenesis by EGFR are thought to be caused by the binding ligands TGFα and EGF, which have shown to function as chemoattractants for endothelial cells and promote the expression of VEGF by tumor cells." (PMID 31303863, 2019). "Knockdown of EGFR, AREG or TGFα expression resulted in decreased tumor cell motility, slower growing tumor cells, and increased survival." (PMID 31681327, 2019). "Overexpression of AREG, TGFα or both ligands increased tumor burden, increased tumor vascularity, increased number of infiltrating macrophages, and portended poorer survival." (PMID 31681327, 2019). "For example, co-expression of c-MYC and transforming growth factor-alpha (TGFα) as transgenes in the mouse liver resulted in a dramatic acceleration of neoplasia as compared with the expression of either of these transgenes alone." (PMID 28422055, 2017). "Lastly, an analysis of patient tumor samples reveals an association between RNA expression levels of NRG1, and two EGFR ligands amphiregulin (AREG) and transforming growth factor α (TGFα)." (PMID 28723928, 2017). "In EC, TGFα is highly expressed in the tumor, and during invasion and metastasis, however, the mechanism regulating this high expression has not been determined." (PMID 26843615, 2016). "MiR-490-3P transfection also suppressed tumor development and TGFα expression (as determined by immunohistochemistry and western blotting) in vivo in the xenograft mouse model." (PMID 26843615, 2016). "Both TGFA mRNA expression and TGFA protein expression were upregulated in tumor tissues compared with adjacent normal tissues." (PMID 27458156, 2016). "Immunohistochemistry (IHC) and Western Blotting indicated that TGFα expression in the tumor xenografts of hsa-miR-490-3p-treated nude mouse was decreased compared with that in mock nude mice." (PMID 26843615, 2016). "Here, we report that miR-505 functions as a tumor suppressor in EC by targeting and regulating TGFA." (PMID 26832151, 2016). "By contrast, in a group of 68 patients with early laryngeal cancer treated with RT, the recurrence rate was significantly higher in patients with tumor showing TGFα expression detected by IHC." (PMID 27556186, 2016). "Our data indicated that TGFA expression was increased in OS tissues compared with adjacent non-tumor tissues and that TGFA promoted OS cell growth in vitro." (PMID 27458156, 2016).
tumor (continued). "Here, the authors show that RHBDD1, a rhomboid intramembrane serine protease, promotes tumor growth in colorectal cancer via cleavage and secretion of TGFα, and activation of the EGFR/Raf/MEK/ERK signalling pathway." (PMID 26300397, 2015). "The upregulation and activation of epidermal growth factor receptor (EGFR) and its ligand, transforming growth factor alpha (TGF-α), have been observed in several tumor types." (PMID 25866816, 2015). "Another postulated mechanism is the action of epidermal growth factor, transforming growth factor-alpha and insulin-like growth factor secreted by the tumour cells themselves, which can lead to the cutaneous changes." (PMID 26152120, 2015). "The important role of TGFα in tumor cell growth was further confirmed by proliferation assay, colony formation assay and soft agar assay." (PMID 26300397, 2015). "It is also worth noting previously determined significant correlations between serum levels of TGFA and interleukin-6, circadian patterns in wrist activity and serum cortisol, as well as tumour-related symptoms in patients with metastatic colorectal cancer." (PMID 25278152, 2014). "The actual mean intensity expression analysis in the clinical prostate database showed that AREG, EREG, and TGFA levels increased in metastatic tumor samples." (PMID 25004126, 2014). "Among those are VEGF, platelet-derived growth factor (PDGF) and transforming growth factor alpha (TGF-α) which all have active roles in tumor angiogenesis and progression." (PMID 24970796, 2014). "Then, accumulated HIF consequently upregulates HIF target genes such as VEGF, GLUT1, PDGF, and TGFα, which facilitate tumor growth." (PMID 24684806, 2014). "Several other factors that promote angiogenesis and tumor cell invasion were also preferentially expressed in the microenvironment of TGFα-positive tumors." (PMID 23986907, 2013). "In this phase apoptosis contributes to local inflammatory conditions and release of tumor promoting cytokines, such as TGFα." (PMID 24339898, 2013). "A closer inspection of the tumor-infiltrating macrophages in TGFα-positive tumors showed that these cells express the lymphangiogenic growth factor VEGFC." (PMID 23986907, 2013). "Dietary selenium or selenoprotein status did not significantly affect tumor incidence and multiplicity but high levels of dietary selenium (0.4 or 2.25 versus 0.1 ppm) inhibited tumor size in TGFα-driven hepatocarcinogenesis." (PMID 23460847, 2013). "The average values and standard deviations of the EGFR concentration (EGFR_s) and the phosphorylated TGFα-EGFR complex concentration (phos_TGFaEGFR_s) in the tumor cell cytomembrane were calculated." (PMID 22394427, 2012). "HIF also activates platelet-derived growth factor (PDGF) and Transforming growth factor alpha (TGF-α) production, which are key factors in angiogenesis and tumor progression." (PMID 23326741, 2012). "Human transforming growth factor alpha (hTGFα) is a native ligand co-overexpressed with its receptor EGFR in many human tumours." (PMID 21176167, 2010). "Nevertheless, the affinity of TGFα3L with EGFR is weaker than that of full length TGFα, which raised a concern for its ability to bring superantigen to the tumour in vivo." (PMID 21176167, 2010). "Among these, four EGFR ligand/EGFR pairs emerged, and in particular, TGFA was robustly upregulated in the in vitro model (14.22-fold) as well as in the PTC tumor samples (range: 3.3–5 fold)." (PMID 20877637, 2010). "After one week, half of the mice of each experimental group (Mock, EGFR-L858R and TGFα) received doxycycline to silence MET in the tumor." (PMID 20500904, 2010). "Both the analyses identified the coordinated expression of the TGFA/EGFR L/R pair in tumor samples when compared with normal tissue." (PMID 20877637, 2010). "SPP1 and TGFA further enhance proliferation and tumor growth." (PMID 41303451, 2025).
tumor (continued). "Further growth factors, such as insulin like growth factor (IGF-1), epidermal growth factor (EGF) and TGFα might also present an autocrine action relevant for tumor proliferation, as their receptors are present in NEN." (PMID 40214893, 2025). "Existing literature suggests that MAN manifestations are mediated by tumor-secreted peptide growth factors (e.g., transforming growth factor alpha [TGF-α]) that activate the epidermal growth factor receptor (EGFR) to induce epidermal hyperplasia and pigmentation." (PMID 41357602, 2025). "CNIH4 may amplify the oncogenic effects of TGFα signaling, thereby advancing tumor progression and metastasis." (PMID 40051704, 2025). "As a result, TGFA has the potential to be exploited as a molecular target for tumour treatment." (PMID 38152044, 2024). "As a result, TGFA may be involved in controlling tumour cell proliferation and migration via this mechanism." (PMID 38152044, 2024). "Collectively, our results suggest that in chemoresistant HNSCC patients, rCAF is the main supplier of TGFα in the tumor microenvironment, which may affect cancer cell chemoresistance via the TGFα-EGFR paracrine signaling." (PMID 37821657, 2023). "However, the underlying mechanism behind this synergetic effect and the source of TGFα in the tumor microenvironment hasn’t been fully exploited." (PMID 37821657, 2023). "Importantly, we also showed that higher expression of CAF-TGFα or tumor-TGFα defined worse overall survival and escalated cancer stage progression in HNSCC patients." (PMID 37821657, 2023). "As the pathogenesis, the crossed reactions between tumor antigens and growth factor receptors on epidermal cells and/or the cutaneous changes by the action of epidermal growth factor, transforming growth factor alpha and insulin-like growth factor secreted by the tumor cells are proposed." (PMID 35713794, 2022). "Furthermore, the uniquely comprehensive histological analysis of the tumor tissue revealed that all layers of tumor lesions of the TGFα/c-myc model are reached, even in larger tumors comprising a border, first layer, second layer, and core." (PMID 35053588, 2022). "The results found that the expression levels of ABCG1, HAVCR2, CD14, and TGFA were significantly increased (p < 0.05) in tumor tissue samples compared with para-cancerous control tissue samples, while the expression levels of KDF1 and KITLG were significantly decreased (p < 0.05)." (PMID 35774505, 2022). "Likewise, increased expression of IL1A (log2 fold change = −4.15) and TGFA (log2 fold change = −2.28) was observed in the HCC tumor cells leading to increased expression of TME-derived MMP9 and MMP2, respectively." (PMID 33995488, 2021). "In our study, miR-490-3p and miR-505 target TGFα and act as tumor suppressor miRNAs." (PMID 34298609, 2021). "The deregulation of HIF1A and HIF2A results in the up-regulation of various growth factors like vascular endothelial growth factor (VEGF), platelet-derived growth factor beta (PDGFB), and transforming growth factor alpha (TGFA) responsible for the development of the tumor." (PMID 32300145, 2020). "TGFα was implicated as a potential signaling molecule produced by tumor cells that could induce macrophage differentiation, which was validated using a CRISPR knockout of TGFA in the OVCAR5 cell line." (PMID 33069212, 2020). "Because the activation of EGFR and TGFα autocrine loop occurs in changing cysts of multiple target organs, this pathway might be exploited as a potential target for anti-tumor therapy for VHL patients." (PMID 32432044, 2020).
tumor (continued). "In addition, EGFRvIII GBM cells secrete increased amounts of different cytokines including TGF-β1 and TGFα but also other hormones like Insulin which promote tumour growth in a paracrine way." (PMID 32052089, 2020). "Moreover, it keeps tumor growth local through repression of pro-metastatic TMED9-TGFα signaling via its downregulation of TMED9, CNIH4, TGFA, and GLI1." (PMID 31253868, 2019). "A four quadrant model of a brain slice was fed glucose and transforming growth factor alpha and monitored for volumetric tumor growth, tumor heterogeneity, expansion rate per tumor region, expansion rate per clone, phenotypic spectrum per tumor clone, and molecular phenotype switching profiles." (PMID 29228953, 2017). "Many studies indicate that aberrant TGFα/EGFR signaling is involved in tumor progression." (PMID 22672900, 2012). "Our data suggest that paclitaxel may exert a self-limiting effect on its ability to kill and reduce the proliferation of autocrine-regulated tumor cells, potentially by increasing both the rates of transcription and activation of TGFα." (PMID 21255411, 2011). "On the other hand, LIV-1 expression may also be stimulated by growth factors in the tumor microenvironment, since treatment with TGFα, TGF-β1, EGF, IGF-1 and β2-M all enhanced the LIV-1 level." (PMID 22110740, 2011). "Among them, TGFa and aFGF appear to be the major growth factors produced by tumor cells and may therefore be the main contributors to the progression of HCC." (PMID 18959789, 2008). "In these 13 cases, about 30–70% of the tumor cells were moderately to strongly positive for TGFα." (PMID 16822304, 2006). "Moreover, increased tumor production of transforming growth factor alpha (TGF-α) may drive keratinocyte proliferation, contributing to paraneoplastic AN." (PMID 39507165, 2024). "Also, autocrine or paracrine ligand-to-receptor loops could potentially activate EGFR, as co-expression of EGFR and TGFa was detected in the same tumor." (PMID 26646697, 2016). "The novel angiogenesis module integrated into the agent-based tumor model is based on a set of reaction–diffusion equations that describe the spatio-temporal evolution of the distributions of micro-environmental factors such as glucose, oxygen, TGFα, VEGF and fibronectin." (PMID 22935054, 2012). "In DEN-CCl4 HCC mice the majority of animals showed an iRGD-induced increase of the blood AFP level, whereas in TGFα/c-myc mice this was only found in a portion of the HCC mice, probably due to AFP expression only in a portion of HCCs in this tumour model." (PMID 38889481, 2024). "As only mice with AFP expressing HCCs can show an iRGD-induced tumour-to-blood transport of AFP, we examined the levels of APF in tumours and corresponding livers of TGFα/c-myc HCC mice by immunoblotting." (PMID 38889481, 2024). "In conclusion, reducing TGFA expression can reduce the incidence, metastasis and invasiveness of CESC while enhancing the anti‐tumour immune response." (PMID 38152044, 2024). "Correlation analysis of six prognostic MDGs (ABCG1, KDF1, KITLG, TGFA, HAVCR2, and CD14) and six types of immune infiltrating cells, including tumor purity, B cells, CD8+T cells, CD4+T cells, macrophages, neutrophils, and dendritic cells was performed." (PMID 35774505, 2022). "Transforming growth factor alpha (TGFα) is a natural ligand for epidermal growth factor receptor (EGFR), a receptor highly expressed in tumor cells." (PMID 36297535, 2022). "Analysis of the five hypoxia- and immune-related genes also showed high expression of EPO, TGFB1, TGFA, and PLAUR, but low expression of TEK in tumor samples." (PMID 35222525, 2022).
tumor (continued). "Data on the FGF2, FGFBP1, TGFA, TGFBR3, and IGF1R expression levels were analyzed using TIMER 2.0 that matched TCGA tumor tissue with normal tissue." (PMID 36430763, 2022). "We found that TGFA, SHC1, PIK3CD, GAB1, and AKT3 were negatively correlated with six tumor immune cells in KIRC, and EIF4EBP1 was positively correlated with macrophage infiltration." (PMID 35903358, 2022). "In the Hif1α signaling pathway, TME-derived growth factors IGF and EGF are likely promoting HCC-tumor derived ARNT, which is in turn promoting the expression of known pro-angiogenesis genes PAI1, and TGFA." (PMID 33995488, 2021). "Among the down-regulated genes, GLI1 and some other tumor progression related genes were discovered, for example, MMP1, MMP9, NFKB2, TGFA, and EGFR." (PMID 33637972, 2021). "ADAM-12 exhibits catalytic activity by cleaving certain ligands that are biologically important for tumour growth, such as tumour necrosis factor-alpha (TNF-α), epidermal growth factor (EGF), and transforming growth factor-alpha (TGF-α)." (PMID 32386517, 2020). "This inhibition was further correlated with the downregulation of proangiogenic molecules like Ki-67 in tumor samples, whereas the expression levels of VEGF, TGFA, and FGF were downregulated at mRNA level." (PMID 31416135, 2019). "Transforming growth factor alpha (TGFα), FGF-2, and EGF were increased in the G59 PDX group compared to the G68 PDX group suggesting a more angiogenic tumor profile in the less cachectic G59 PDX group." (PMID 30513792, 2018). "The tumor angiogenesis is controlled by a large number of proangiogenic factors such as transforming growth factor beta 1 (TGF-β1), transforming growth factor alpha (TGF-α), and vascular endothelial growth factor (VEGF)." (PMID 28293063, 2017). "It is suggested that TGFα pathway and the autocrine activation of EGFR, leading to tumor growth, apoptosis inhibition and metastasis play a role in this process." (PMID 27055285, 2016). "Additional ligand-neutralizing antibodies targeting TGFα or HB-EGF have demonstrated anti-proliferative activity in vitro and inhibition of tumor growth and high dose-tolerability in vivo." (PMID 27153091, 2016). "After TGFα overexpression was induced with zinc sulfate water for eight months, the pancreata of the STP, MT-TGFα, and S4 mice were examined for tumor development and fibrotic responses." (PMID 25803032, 2015). "We have identified candidate gene expression (TGFa, PECAM1, and NRG1) in tumor for the prediction of sorafenib response and PFS by RNA sequencing." (PMID 26046304, 2015). "For selective targeting to tumor cells, we fused the epidermal growth factor receptor (EGFR) peptide ligand transforming growth factor α (TGFα) to human pre-pro-GrB." (PMID 23573299, 2013). "The expression levels of TGFα, EGF, and EGFR have been shown to correlate with progressive tumor growth, development of metastasis, and resistance to chemotherapy." (PMID 23986907, 2013). "Priming by tumor cells upregulated EREG, TGFA and OSM transcripts in PBMC within 24 hrs, as shown by qPCR analysis." (PMID 23597096, 2013). "In NSClines, HGH induces the strongest chemotactic response from a variety of multiple tumor-derivedgrowth factors including vascular endothelial growth factor (VEGF), epidermal growth factor (EGF)and transforming growth factor alpha (TGF-α)." (PMID 23637756, 2013). "The altered fibroblasts produced TGFα and hepatocyte growth factor (HGF) which resulted in accelerated tumour cell growth." (PMID 24090133, 2013). "Concurrently, there is a marked downward trend of the phosphorylated transforming growth factor-α (TGFα)-EGFR complex in the tumor cell cytomembranes, which indicates restriction of tumor growth after CTL immunotherapy." (PMID 22394427, 2012). "We observed that TGFα, via EGFR, promoted proliferation of KGN and COV434 cells and facilitated KGN tumor cell migration." (PMID 23155381, 2012).